NLRP3 (NLR family pyrin domain containing 3)
Diseases named in the same sentence as NLRP3 in open-access papers (continued):
Sharing a sentence is not in itself a finding about the gene and the disease.
acute pancreatitis (continued). "Among them, NLRP3 inflammasome dependent pyroptosis is a key factor in the pathogenesis of acute pancreatitis, the necrosis related molecule GSDMD may be an independent prognostic biomarker for AP." (PMID 40620677, 2025). "Furthermore, butyrate has been shown to reduce pancreatic injury in acute pancreatitis by downregulating inflammatory mediators and inhibiting activation of the NLRP3 inflammasome." (PMID 41277964, 2025). "NLRP3 inflammasome-dependent pyroptosis is a key factor in the pathogenesis of acute pancreatitis." (PMID 40620677, 2025). "In addition, butyrate can reduce pancreatic damage during acute pancreatitis (AP) by eliminating inflammatory factors and inhibiting NLRP-3 inflammatory vesicles." (PMID 40860654, 2025). "Moreover, in obese mice with severe acute pancreatitis, orlistat alleviated adipose tissue necrosis by inhibiting the NLRP3-caspase 1 inflammasome pathway of adipose tissue macrophages." (PMID 38468241, 2024). "Similarly, pinocembrin, pramipexole, proanthocyanidins, and Emodin inhibit NLRP3-mediated caspase-1-1 activation and IL-1β production in animal models of acute pancreatitis." (PMID 39769450, 2024). "Furthermore, polydatin has been identified as a promising therapeutic agent that, by targeting different states of the NLRP3 inflammasome complex, shows potential in treating acute pancreatitis (AP) and other NLRP3-related inflammatory diseases." (PMID 39691768, 2024). "Importantly, genetic and pharmacological inactivation of HSP90α effectively reduced NLRP3 inflammasome activation and alleviated cerulein-induced acute pancreatitis." (PMID 39691768, 2024). "Studies have found that emodin can reduce the increased expression of NLRP3, ASC, caspase-1 p10, and GSDMD proteins in alveolar macrophages induced by acute pancreatitis and improve pancreatitis-associated lung injury by inhibiting macrophage pyroptosis pathway." (PMID 38671352, 2024). "NLRP3, ASC, and caspase-1 are involved in inflammation associated with acute pancreatitis as loss of any of these signaling components has been shown to reduce the severity of acute pancreatitis." (PMID 38585277, 2024). "Meanwhile, emodin could protect acetaminophen-induced hepatotoxicity via the inhibition of NLRP3 activation in C57BL/6 mice and protect pancreatic ductal cells against ATP-induced acute pancreatitis through the inhibition of the P2 × 7/NLRP3 signaling pathway." (PMID 35265148, 2022). "CTSB may aggravate acute pancreatitis (AP) by activating the NLRP3 inflammasome and promoting caspase-1-induced pyroptosis." (PMID 36552871, 2022). "Inhibiting the activation of NLRP3 inflammasome may be an effective strategy for preventing and treating acute pancreatitis." (PMID 36327405, 2022). "To determine whether pyroptosis is responsible for STC-induced acute pancreatitis, we detected NLRP3 (inflammasome sensor), caspase-1, and GSDMD expression by Western blotting in vivo and in vitro." (PMID 34422214, 2021). "During experimentally induced systemic inflammatory conditions (e.g., acute pancreatitis and acute hepatitis) Lac may downregulate Toll-like receptor 4, NLRP3 (NACHT, LRR, and PYD domains-containing protein 3) inflammasome, and concomitantly IL-1β." (PMID 28499395, 2017). "MCC950 could inhibit the expression of NLRP3 inflammasome in the pancreas of acute pancreatitis mice, as well as the expression of caspase-1 in the small intestine and down-regulate the expression of cytokines, thus alleviating pancreatic and intestinal injury." (PMID 36327405, 2022). "These tsRNAs influence the progression of pancreatic cancer and acute pancreatitis by modulating various pathways, including ZBP1/NLRP3, Hippo, PI3K/AKT, glycolysis/gluconeogenesis, and Wnt signaling." (PMID 39896345, 2025). "Bifidobacterium and its metabolite lactic acid suppress systemic inflammation and attenuate acute pancreatitis by modulating the Toll-like receptor 4 (TLR4)/MyD88 and NLRP3/Caspase-1 signaling pathways." (PMID 41277964, 2025).
acute pancreatitis (continued). "In acute pancreatitis, upregulation of S100A9 induces cell injury and inflammatory response through activating NLRP3 via targeting VNN1-mediated ROS release." (PMID 36527111, 2022). "Acute pancreatitis, which has been described in COVD-19 patients and is worse in diabetics, also activates the NLRP3 inflammasome." (PMID 33149733, 2020). "In the present study, we investigated whether activation of AMPK by AICAR limits the inflammatory response and oxidative stress in the progression of PALI in two rodent models of severe acute pancreatitis (SAP) via Nrf2-mediated antioxidant effects and NLRP3 inflammasome activation." (PMID 34531748, 2021).
atrial fibrillation (59 papers, 2018 to 2026). A disorder characterized by an electrocardiographic finding of a supraventricular arrhythmia characterized by the replacement of consistent P waves by rapid oscillations or fibrillatory waves that vary in size, shape and timing and are accompanied by an irregular ventricular response. "In a hyperuricemic state, activation of the NLRP3 inflammasome can also promote inflammation, closely resembling the pathogenic mechanism of atrial fibrillation." (PMID 40469443, 2025). "Studies have demonstrated that activation of the NLRP3 inflammasome in atrial myocytes is a potential pathogenic mechanism for atrial fibrillation." (PMID 40469443, 2025). "There has also been evidence that the NLRP3 inflammasome is linked to atrial fibrillation progression." (PMID 37123477, 2023). "Specifically, the NLRP3 inflammasome has been linked to clinical atrial fibrillation, presumably reflecting an inflammatory state." (PMID 35406727, 2022). "Furthermore, activation of the NLRP3 inflammasome in an atrial fibrillation rat model has been shown to be closely associated with elevated IL-1β expression in myocardial tissue." (PMID 41561130, 2025). "Microbiota transplantation in animal models, or selective inhibition of NLRP3, reduced the fibrosis process and the arrhythmia susceptibility, underlining the role of systemic inflammation related to dysbiosis as a pathogenetic element of atrial fibrillation." (PMID 38892223, 2024). "The NLRP3 inflammasome has also been implicated in the development of atrial fibrillation." (PMID 38177104, 2024). "In addition, microbial dysbiosis causes impaired glucose tolerance and enhanced NLRP3 inflammasome activity, leading to an increase in atrial fibrillation (AF) susceptibility in elderly patients and animal models." (PMID 36111168, 2022). "This study was aimed at exploring whether silencing of TLR4 could inhibit atrial fibrosis and susceptibility to atrial fibrillation (AF) by regulating NLRP3-TGF-β in hypertensive rats." (PMID 35860690, 2022). "In murine cardiomyocytes, NLRP3 inflammasome activation predisposes to ectopic electrical activity and drives both structural and electrophysiological remodeling (e.g. fibrosis and altered potential duration) that support the initiation and the progression of atrial fibrillation." (PMID 41272654, 2025). "These limitations underscore the need for novel, orally bioavailable small-molecule inhibitors that selectively target NLRP3 inflammasome signaling in atrial fibrillation, offering improved tolerability and therapeutic precision." (PMID 40649732, 2025). "Its gene (NLRP3) increased expression in leukocytes has been shown during atrial fibrillation; its role in changing the phenotype of macrophages has been demonstrated, while its role in granulocytes remains poorly studied." (PMID 41440382, 2025). "While anakinra is approved for NLRP3-related diseases such as rheumatoid arthritis, its potential in atrial fibrillation remains untested." (PMID 40649732, 2025). "This process triggers intracellular signaling cascades, leading to increased NLRP3 expression, promotion of myocardial fibrosis, and further acceleration of the progression of atrial fibrillation." (PMID 40411704, 2025). "In particular, DBIL suppresses NF-κB signaling and NLRP3 inflammasome activation, countering key drivers of atrial fibrillation and thrombosis." (PMID 41425979, 2025). "Although the majority of inflammasome research in cardiac electrophysiology has focused on atrial fibrillation, a growing body of evidence implicates NLRP3 inflammasome activation in the initiation and perpetuation of ventricular arrhythmias." (PMID 40649732, 2025). "Given its central role in the pathogenesis of atrial fibrillation, the NLRP3 inflammasome represents an attractive therapeutic target." (PMID 40649732, 2025).
atrial fibrillation (continued). "According to the study of Li and colleagues, NLRP3 inflammasome activity was enhanced in the cardiomyocytes of patients with atrial fibrillation (most common cardiac arrhythmia)." (PMID 41272654, 2025). "Activation of the NLRP3 inflammasome is upregulated in the atria of patients with atrial fibrillation, and inhibition of NLRP3 signaling has been demonstrated to mitigate atrial fibrillation in animal models." (PMID 38650023, 2024). "Studies on rabbits utilizing ziprasidone, which induces atrial arrhythmia, including atrial fibrillation (AF), have shown increased activation of the NLRP3 inflammasome and ROS production via the PI3K/Akt/mTOR pathway." (PMID 39594530, 2024). "In HFpEF patients with atrial fibrillation, NLRP3 inflammasome expression levels were significantly elevated compared to patients with atrial fibrillation alone and also correlated with the H2FPEF score." (PMID 39407935, 2024). "In animal models, age-related intestinal dysbiosis promotes atrial fibrillation through increased levels of lipopolysaccharide and glucose, with the activation of the NLRP3 inflammasome, leading to atrial tissue fibrosis." (PMID 38892223, 2024). "It has been shown that NLRP3 inflammatory vesicle activity is significantly elevated in cardiomyocytes from patients with atrial fibrillation, which has implications for cardiac fibroblast activation." (PMID 37583579, 2023). "In patients with atrial fibrillation, the NLRP3 inflammasome is up-regulated, and its activity in the cardiomyocyte correlates with the progression of atrial fibrillation to more persistent forms." (PMID 38068879, 2023). "The relationship between atrial fibrillation and inflammation, especially the NLRP3 inflammasome, which is involved in the pathogenesis of atrial fibrillation, has recently attracted increasing attention." (PMID 38073096, 2023). "The NLRP3 inflammasome is elevated in atrial myocytes in patients with atrial fibrillation (AF) (be it paroxysmal or long-standing)." (PMID 37762961, 2023). "One recent study showed that the expression of activated components of NLRP3 is increased in atrial whole-tissue homogenates and cardiomyocytes from patients with postoperative atrial fibrillation (POAF)." (PMID 37123477, 2023). "Rationale: Dysbiotic gut microbiota (GM) and NLRP3 inflammasome are proarrhythmic factors in atrial fibrillation (AF)." (PMID 35844801, 2022). "Genetic inhibition of NLRP3 prevents spontaneous AF in CREM-transgenic mice (a well-characterized mouse model of spontaneous AF), which is sufficient to illustrate the importance of NLRP3 in atrial fibrillation." (PMID 35296647, 2022). "The NLRP3 inflammasome is upregulated in the atrial tissue of atrial fibrillation patients and the inhibition of NLRP3 reduces atrial fibrillation inducibility in cardiomyocyte-specific knock-in mouse models expressing constitutively active NLRP3." (PMID 32987834, 2020). "The mechanism of action of the NLRP3 inflammasome in the pathogenesis of arrhythmia after heart failure and atrial fibrillation (AF) is summarized below." (PMID 31354731, 2019). "In this review, we will focus on the very recently established role of the NLRP3 inflammasome in cardiac cells and its potential involvement in cardiac diseases, such as cardiomyopathies and atrial fibrillation (AF)." (PMID 30150941, 2018). "In particular, the infiltration of M1-type macrophages has been shown to significantly increase in persistent AF, accompanied by elevated levels of IL-1β and NLRP3 expression, suggesting that the activation of inflammatory pathways plays a key role in atrial fibrillation." (PMID 41561130, 2025). "The most common arrhythmia affecting people worldwide, which is atrial fibrillation (AF), could also be affected by NLRP3, considering that inflammation drives the pathophysiology of AF, as well as obesity, diabetes, hypertension, and HF." (PMID 40305215, 2025).
atrial fibrillation (continued). "Notably, fibroblast-restricted NLRP3 activation has been shown to promote atrial fibrillation and diastolic dysfunction via increased IL-1β secretion and intercellular crosstalk with cardiomyocytes, culminating in electrical remodeling and calcium mishandling." (PMID 40649732, 2025). "Among these, the NLRP3 inflammasome has emerged as the most extensively characterized and clinically significant due to its involvement in a diverse array of inflammatory and cardiovascular pathologies, including atrial fibrillation." (PMID 40649732, 2025). "NLRP3 activation in cardiomyocytes also enhances a specific potassium current (IKur), shortening the atrial refractory period and facilitating the formation of re-entry substrates-another mechanism that maintains atrial fibrillation." (PMID 41272654, 2025). "Furthermore, SCFA was found to alleviate atrial remodeling in patients with atrial fibrillation through GPR43/NLRP3 signaling pathway." (PMID 38084144, 2023). "Btk contributes to the development of atrial fibrillation by affecting NLRP3." (PMID 35296647, 2022). "HD, like atrial fibrillation (AF), involves NF-κB activation, which, in turn, drives the activation of the NLRP3 inflammasome." (PMID 39941553, 2025). "In the development and progression of atrial fibrillation (AF) and AS, gut microbiota metabolites play a critical role by activating the NLRP3 inflammasome." (PMID 39568773, 2024). "Recent protocols have identified the NLRP3 inflammasome as a crucial factor in the development of cardiomyopathies and atrial fibrillation (AF), suggesting a potential pathway for novel therapeutic agents." (PMID 39594530, 2024). "In models where atrial fibrillation is induced by Ang II, inhibition of TREM-1 markedly reduces macrophage infiltration, diminishes NLRP3 activation, and suppresses the overall inflammatory response, ultimately ameliorating electrical remodeling in the atria." (PMID 41561130, 2025). "By suppressing NLRP3 expression, MCC950 attenuates the inflammatory response and mitigates the progression of atrial fibrillation." (PMID 40411704, 2025). "NLRP3 inflammasome inhibitor (MCC950) has also been shown to improve spontaneous atrial premature beats and induce atrial fibrillation in CM-KI mice." (PMID 35187131, 2022). "In addition, enhanced cardiomyocyte (CM) NLRP3 inflammasome signaling promotes atrial fibrillation (AF)." (PMID 36189207, 2022). "NLRP3 inflammasome also plays an important role in the development of atrial fibrillation (AF)." (PMID 34210954, 2021). "Recent preclinical evidence has suggested that the NLRP3 inflammasome may play a prominent role in the pathogenesis of atrial fibrillation (AF)." (PMID 34337581, 2021). "Furthermore, studies demonstrate that the NLRP3 inflammasome directly contributes to POAF development and is upregulated in patients with prevalent forms of atrial fibrillation, including paroxysmal, persistent, and POAF." (PMID 40868251, 2025). "In a previous study on atrial fibrillation, hypertrophic adipocytes and activated macrophages secreted tumor necrosis factor‐α and interleukin‐6 (IL‐6) to activate NOD‐like receptor family protein‐3 (NLRP3) inflammatory pathway and promote atrial fibrosis and electrical remodeling." (PMID 37707300, 2023).
chronic obstructive pulmonary disease (58 papers, 2016 to 2026). A chronic and progressive lung disorder characterized by the loss of elasticity of the bronchial tree and the air sacs, destruction of the air sacs wall, thickening of the bronchial wall, and mucous accumulation in the bronchial tree. "A large number of studies have demonstrated that NLRP3 inflammasomes are associated with the pathogenesis of a variety of respiratory diseases, such as rhinitis, asthma, and chronic obstructive pulmonary disease (COPD)." (PMID 38256101, 2024). "The NLRP3 inflammasome is a cytosolic protein complex that senses cellular stress or damage and initiates inflammatory responses, which has been implicated in various pulmonary diseases, such as asthma and chronic obstructive pulmonary disease (COPD)." (PMID 37175715, 2023). "Previous studies suggest that the downstream products of NLRP3 inflammasomes such as IL-1β or IL-18 are associated with the pathophysiology of smoke-driven chronic obstructive pulmonary disease (COPD) although direct evidence to link NLRP3 protein with the disease is sparse." (PMID 28056996, 2017). "Increased NLRP3 inflammasome activity has been implicated in chronic obstructive pulmonary disease (COPD) and steroid-resistant asthma." (PMID 41395250, 2025). "Chronic obstructive pulmonary disease (COPD), a disease characterized by progressive airflow obstruction, emphysema, and inflammation within the lungs, has been associated multiple times with NLRP3 inflammasome." (PMID 34202842, 2021). "NLRP3, an inflammasome, is significantly upregulated in chronic obstructive pulmonary disease (COPD) models." (PMID 40906358, 2025). "For example, daphnetin prevented chronic obstructive pulmonary disease through mitigating NLRP3-mediated inflammation and pyroptosis." (PMID 39257395, 2024). "Current studies have confirmed that the increased expression level of NLRP3 inflammasome is closely related to the occurrence and progression of chronic obstructive pulmonary disease, malignancy, and chronic viral hepatitis." (PMID 35169393, 2022). "Previous studies have shown that the abnormal activation of the NLRP3 inflammasome leads to an array of disease pathologies, including allergic airway disease, chronic obstructive pulmonary disease, and asbestosis." (PMID 34457117, 2021). "However, NLRP3 inflammasome activation has emerged as a key contributor to pathological remodeling processes of cardiac arrhythmias." (PMID 41272654, 2025). "SCFAs (acetate, propionate, and butyrate) can enhance the expression of GPR43 while downregulating the expression of NLRP3, IL-18, and IL-1β, thereby strengthening the mucosal immune function of the gut and lungs in rats with chronic obstructive pulmonary disease." (PMID 40906358, 2025). "However, diabetic mice with Nlrp3 and Caspase-1 deletion showed lower vulnerability and reduced severity of cardiac arrhythmia." (PMID 37336361, 2023). "Moreover, T2D mice were observed with increased sterile inflammation via upregulated TLR2 and NLRP3 inflammasome-mediated IL-1β production in myocardial macrophages, which led to cardiac arrhythmias." (PMID 37336361, 2023). "In this sense, chronic obstructive pulmonary disease (COPD) is characterized by a strong prooxidant state and mitochondrial dysfunction, which causes the activation of the NLRP3 inflammasome and the consequent cytokine storm usually observed in this lung pathology." (PMID 33919780, 2021). "Correspondingly, blocking LPS/TLR4/NLRP3 signaling might lesson inflammation-related cardiac arrhythmia." (PMID 34201938, 2021). "Finally, BML-111 exerts anti-inflammatory effects in a chronic obstructive pulmonary disease (COPD) mouse model by preventing NLRP3 inflammasome activation and inhibiting ROS production through NRF2 upregulation." (PMID 33321955, 2020). "Our evidence, well in line with the literature, suggests that NLRP3 inflammasome activation may also be involved in chronic obstructive pulmonary disease." (PMID 32244997, 2020).